ALB (albumin)
Diseases named in the same sentence as ALB in open-access papers (continued):
Sharing a sentence is not in itself a finding about the gene and the disease.
listeriosis (1 paper, 2024). A bacterial infection caused by Listeria monocytogenes. "We are the first to show this connection in listeriosis, and we recommend using albumin levels to identify high-risk patients." (PMID 39597753, 2024). "However, the role of albumin in predicting death in listeriosis is poorly understood." (PMID 39597753, 2024).
liver tumor (1 paper, 2022). "As another type of liver tumor containing multinuclear giant cells, sarcomatoid HCC is featured by reactivity for CK 8, ALB, and fibrinogen, as well as for VIM." (PMID 36698409, 2022).
lumbar disk herniation (1 paper, 2024). "Proteins with significant serum–cerebrospinal fluid correlation in expression, analyzed regarding the associations between normalized albumin quotient and expression quotient (cerebrospinal fluid/serum), in patients with degenerative disk disease and patients with lumbar disk herniation." (PMID 38900144, 2024). "Proteins with significant serum–cerebrospinal fluid correlation in expression, analyzed regarding the associations between normalized albumin quotient and cerebrospinal fluid expression of each respective protein, in patients with degenerative disk disease and patients with lumbar disk herniation." (PMID 38900144, 2024).
macular edema (1 paper, 2016). "In patients with clinically significant macular edema (n = 54), higher systolic blood pressure and urinary albumin excretion were observed." (PMID 27200379, 2016).
Marfan syndrome (1 paper, 2021). A disorder of the connective tissue. "It was found that low ischemia-modified albumin level (<=72.50 μ/ml), surgical treatment, and the presence of Marfan syndrome chiefly led to the prediction error in the XGBoost model." (PMID 34604356, 2021).
mastocytosis (1 paper, 2025). A clonal myeloproliferative neoplasm characterized by the proliferation and accumulation of neoplastic mast cells in one or multiple organs or organ systems. "In the event of abnormalities in the CBC, platelets, or liver tests, or of a decrease in serum ALB, a further bone marrow assessment and imaging examinations specifically to screen for an advanced form of mastocytosis will be necessary." (PMID 41039576, 2025). "In the event of new bone pain, blood tests are indicated to check the CBC, perform an LFT, and determine albumin levels, which, together with abdominal ultrasound and X-rays can rule out any worsening of mastocytosis." (PMID 41039576, 2025).
Meconium ileus (1 paper, 2022). Obstruction of the intestine due to abnormally thick meconium. "Age of surgery, multifetation, weight on admission, preoperative leukocytes, albumin and C-reaction protein, operation time, meconium ileus, intestinal perforation, pulmonary infection, mesenteric dysplasia, and number of anastomosis were initially excluded (P > 0.1)." (PMID 36578664, 2022).
membranoproliferative glomerulonephritis type I (1 paper, 2016). "A renal biopsy confirmed membranoproliferative glomerulonephritis type I. Curative therapy for the malignancy was not possible, so treatment was commenced with prednisolone with consequential biochemical improvement in renal function and proteinuria, although his serum albumin remained low." (PMID 27439394, 2016).
Meniere disease (1 paper, 2014). A disease of the inner ear (labyrinth) that is characterized by fluctuating sensorineural hearing loss; tinnitus; episodic vertigo; and aural fullness. "However, this study eliminate serum abundant proteins such as albumin and immunoglobulins for 2-DE analysis and performed LC-MS/MS in the several spots that were different between Meniere's disease and control after image analysis." (PMID 25330336, 2014).
Menkes disease (1 paper, 2014). A usually severe multisystemic disorder of copper metabolism, characterized by progressive neurodegeneration and marked connective tissue anomalies as well as typical sparse abnormal steely hair. "The exact role of l-histidine in copper-albumin interaction (albumin is a copper carrier) in cellular uptake of copper as well as in Menkes disease is not well understood." (PMID 24434671, 2014).
Merkel cell carcinoma (1 paper, 2009). "The primary 99mTc-based agents utilized for radioguided SLN biopsy for Merkel cell carcinoma are either 99mTc sulfur colloid or and 99mTc colloidal human albumin." (PMID 19173715, 2009).
metabolic myopathies (1 paper, 2014). "These genes are closely related with metabolic myopathies, myogenesis, albumin gene expression, and haemolytic anemia." (PMID 25551574, 2014). "VPA alters the expression of PEBP1, BHMT, MYL1, ALB and FLNC that are closely related with metabolic myopathies, myogenesis, albumin gene expression, and haemolytic anemia." (PMID 25551574, 2014).
midgut volvulus (1 paper, 2022). "The constructed nomogram model, which combines the HR, MAP, serum CRP, albumin, serum sodium levels, and pH values, can be a superior tool for predicting intestinal ischemia and necrosis in neonates with midgut volvulus." (PMID 35795333, 2022). "Heart rate, mean arterial pressure, serum C-reactive protein, serum sodium, serum albumin, and pH levels were independent predictors for intestinal ischemia and necrosis in patients with midgut volvulus." (PMID 35795333, 2022).
Miosis (1 paper, 2019). Abnormal (non-physiological) constriction of the pupil. "The amount of drug lost to albumin in tears is therefore insignificant, as only a small fraction of intraocular drug penetration is sufficient to cause miosis." (PMID 32047429, 2019). "The pharmacological activity of latanoprost (i.e. miosis) was also reduced in the presence of albumin in tears, although not to the same extent as for tropicamide." (PMID 32047429, 2019).
multiple endocrine neoplasia type 1 (1 paper, 2019). An autosomal dominant tumor predisposition syndrome caused by pathogenic variants in the MEN1 gene, characterized by an increased risk of tumors of the parathyroid glands, pituitary gland, and foregut neuroendocrine tumors (most commonly pancreatic islet cells). "Prolactin, parathyroid hormone (PTH), albumin, and calcium levels, as well as MRI of his brain were normal, ruling out multiple endocrine neoplasia type 1 (MEN-1)." (PMID 31234935, 2019).
mycobacteriosis (1 paper, 2010). "Further hematological changes indicating a mycobacteriosis are presence of low albumin and low total protein levels, which however, could not be supported by the findings of our study." (PMID 20871867, 2010).
mycoplasma pneumonia (1 paper, 2023). "As core albumin, we used special PSA obtained from porcine blood of SPF swine, which had been reared in clean piggeries and which were guaranteed to be free of certain diseases such as mycoplasma pneumonia." (PMID 37316550, 2023).
Mydriasis (1 paper, 2019). Abnormal dilatation of the iris. "The biological effect of tropicamide (i.e. mydriasis) was significantly reduced in canine eyes that received concurrent topical administration of serum albumin, regardless of the protein’s concentration." (PMID 32047429, 2019).
Myelopathy (1 paper, 2023). Myelopathy is an descriptive term, referring to pathology leading to a neurologic deficit related to the spinal cord. "EDSS scores and CSF ALB levels in patients with increased BBB permeability were significantly higher than in those with normal BBB permeability, and QALB was positively correlated with the length of myelopathy." (PMID 37821922, 2023).
myopia (1 paper, 2025). "Mediation analysis revealed that PFOA and myopia risk were partially mediated by serum albumin (ALB), with a mediation percentage of 22.48% (P = 0.008)." (PMID 40571595, 2025). "Moreover, the serum ALB level was associated with the risk of myopia (OR: 2.21; 95% CI: 1.42–3.44; P < 0.001)." (PMID 40571595, 2025). "Associations between serum ALB concentration and the risk of myopia." (PMID 40571595, 2025). "Higher socioeconomic status is often correlated with improved medical care and elevated serum ALB levels; however, it may also increase the risk of myopia due to prolonged near-work activities." (PMID 40571595, 2025). "To examine the role of the serum ALB concentration in the relationship between the level of PFOA and myopia risk, we performed a mediation analysis." (PMID 40571595, 2025). "The results revealed that the serum ALB concentration significantly mediated the relationship between PFOA level and myopia risk, with a positive effect of 22.48% (P = 0.008)." (PMID 40571595, 2025). "Our findings suggest a potential link between exposure to PFOA and the likelihood of myopia development in young individuals and a mediating effect of serum ALB on this relationship." (PMID 40571595, 2025). "Compared with normal-vision individuals, adolescents with myopia presented with increased serum ALB concentrations (P = 0.018)." (PMID 40571595, 2025). "Mediating effects of serum albumin on association between log-transformed PFAS level and risk of myopia." (PMID 40571595, 2025). "Serum ALB serves as a critical marker of systemic metabolic health, and recent research has highlighted the close relationship between metabolic abnormalities and myopia." (PMID 40571595, 2025). "The results of the mediation analysis suggested that the serum ALB concentration may positively influence the association between PFOA exposure and myopia risk, indicating that elevated serum ALB levels could be a potential risk factor for myopia." (PMID 40571595, 2025). "Additionally, we investigated whether the serum ALB concentration might serve as a potential mediator of the relationship between PFAS exposure and myopia." (PMID 40571595, 2025).
neck cancer (1 paper, 2021). "A previous study demonstrated that the overexpression of SPARC may be associated with response to nanoparticle albumin-bound paclitaxel (nab-paclitaxel in neck cancer)." (PMID 34456964, 2021).
neck tumours (1 paper, 2023). "Most participants were diagnosed with pancreatic head and/or neck tumours, and systemic inflammation (NLR ≥ 3 or albumin < 35 g/L) was present in around half of participants at diagnosis." (PMID 37316578, 2023).
neoplastic polyp (1 paper, 2024). "In addition, the low albumin levels in individuals with neoplastic polyps indicate that this parameter can also be used as a marker." (PMID 39459558, 2024). "In particular, inflammatory parameters such as CRP, albumin, PLR, CALLY index, HALP score, PIV, SIII, and SIRI were significantly different in neoplastic polyps compared to nonneoplastic polyps." (PMID 39459558, 2024).
odontogenic cyst (1 paper, 2025). A cyst in the jaw that arises from tissues of tooth development. "Given all the biomedical benefits of albumin and the bone regeneration advantages of albumin-impregnated bone grafts, this study aims to compare the therapeutic effects of placing BoneAlbumin® in the bone cavity after the removal of odontogenic cysts with leaving the defect empty (control group)." (PMID 40565919, 2025).
oligospermia (1 paper, 2018). Decreased number of spermatozoa in the semen. "In light of this, significantly lower seminal plasma albumin level in males with oligospermia than in the controls should be interpret as attenuation of antioxidant defense." (PMID 30116493, 2018). "The level of UA in seminal plasma was significantly higher in males with oligoasthenospermia than in the control group by 19%, while the level of albumin in seminal plasma was significantly lower in males with oligospermia by 12%." (PMID 30116493, 2018).
onchocerciasis (1 paper, 2020). Onchocerciasis is a form of filariasis, caused by the parasitic worm Onchocerca volvulus, transmitted by the black fly. "It is unknown whether ALB plus IVM has an added impact on onchocerciasis adult worm viability and sterility, compared to IVM alone." (PMID 31536624, 2020). "Our results do not suggest that ALB plus IVM is superior to IVM alone for the treatment of onchocerciasis." (PMID 31536624, 2020). "The question of whether IVM plus ALB is superior to IVM alone for onchocerciasis was raised 25 years ago, when Awadzi and Buettner examined the efficacy of a single dose of this combination in onchocerciasis patients." (PMID 31536624, 2020).
open-angle glaucoma (1 paper, 2016). Chronic outflow obstruction of the eye's drainage canals that can lead to increased internal eye pressure and optic nerve damage. "Odds ratios for the presence of open-angle glaucoma among different urinary albumin-to-creatinine ratio tertiles in nondiabetic subjects in the matched cohort." (PMID 28006020, 2016). "Odds ratios for the presence of open-angle glaucoma among different urinary albumin-to-creatinine ratio tertiles in nondiabetic subjects with low-grade albuminuria within the normal range." (PMID 28006020, 2016). "Odds ratios for the presence of open-angle glaucoma among different urinary albumin-to-creatinine ratio tertiles in nondiabetic subjects." (PMID 28006020, 2016).
opioid dependence (1 paper, 2025). "Due to the absence of blood samples from the subjects with opioid dependence, we were unable to measure serum protein levels and thus could not calculate the CSF/serum albumin ratio to assess BBB function." (PMID 40454659, 2025).
oral lichen planus (1 paper, 2012). Oral lichen planus is a chronic inflammatory oral condition of unknown aetiology characterized by T-cell-mediated chronic immune response and abnormal epithelial keratinization cycle. "According to multivariate analysis, three factors - positivity for HCV RNA, low albumin level (< 4.0 g/dL), and history of smoking - were associated with the development of oral lichen planus." (PMID 22490000, 2012).
organophosphorus poisoning (1 paper, 2023). "For instance, researchers created a nomogram with six features, including age, white cells, albumin, cholinesterase, blood pH, and lactic acid levels, for the bedside assessment of patients with acute organophosphorus poisoning." (PMID 36969682, 2023).
otitis (1 paper, 2021). "The otitis-simulating solution was prepared following typical concentration of salts, glucose, albumin, and lysozyme found in serous middle ear effusions (SMEE) of patients with COM with effusion, which is inflammation driven." (PMID 34575515, 2021).
otitis media (1 paper, 2014). Inflammation of the anatomical structures of the middle ear, which is most often caused by an infectious process. "Approximately 3 weeks after dosing this same subject received 14 mg oral ciprofloxacin hydrochloride for otitis media, and albumin tannate for diarrhea." (PMID 25505576, 2014).
Pain (1 paper, 2019). An unpleasant sensory and emotional experience associated with actual or potential tissue damage, or described in terms of such damage. "The fact that high levels of albumin have previously been negatively associated with pain and significantly lower levels of inflammatory cytokines in healthy older subjects indicates that high levels of albumin are not related to pain disorders." (PMID 31687055, 2019).
PEComas (1 paper, 2023). "Recently, nab-sirolimus, an albumin-bound mTOR inhibitor, was approved by the Food and Drug Administration (FDA) for PEComas, which harbor a TSC mutation, and this drug remains the only FDA-approved systemic treatment for these tumors." (PMID 36845725, 2023).
Pediatric inflammatory multisystem syndrome (1 paper, 2022). "Pediatric inflammatory multisystem syndrome temporally associated with SARS-CoV-2 (MIS-C) is characterized by persistent fever and evidence of single or multiorgan dysfunction, and laboratory evidence of inflammation, elevated neutrophils, reduced lymphocytes, and low albumin." (PMID 36361640, 2022).
Peri-Implantitis (1 paper, 2023). An inflammatory process with loss of supporting bone in the tissues surrounding functioning DENTAL IMPLANTS. "We conducted this animal study to assess the efficacy of the novel hydrogel containing zinc oxide-loaded and minocycline serum albumin nanoparticals (Mino-ZnO@Alb NPs) on peri-implantitis in an experimental mouse model." (PMID 37471303, 2023).
periampullary cancer (1 paper, 2022). "On the contrary, a retrospective study which included 79 patients who underwent PD for periampullary cancer considered albumin < 25 g/L as a risk factor for OS." (PMID 35773692, 2022).
pertussis (1 paper, 2025). A contagious bacterial respiratory infection caused by Bordetella pertussis. "Specifically, children diagnosed with pertussis exhibited significantly lower serum IgM, albumin, and globulin levels, indicating a disruption in both immune and nutritional status." (PMID 40539153, 2025). "Regarding immune function, this study found that IgM, albumin, and globulin levels were significantly lower in the pertussis group." (PMID 40539153, 2025). "Conversely, serum IgM (0.72 ± 0.5 g/L versus 0.98 ± 0.8 g/L, p = 0.04), albumin (38.7 ± 4.7 g/L versus 48.4 ± 5.2 g/L, p < 0.01), and globulin levels (14.8 ± 5.7 g/L versus 19.7 ± 5.1 g/L, p = 0.03) were significantly lower in the pertussis group." (PMID 40539153, 2025).
Peyronie disease (1 paper, 2025). A condition characterized by hardening of the penis due to the formation of fibrous plaques on the dorsolateral aspect of the penis, usually involving the membrane (tunica albuginea) surrounding the erectile tissue (corpus cavernosum penis). "We evaluated the Hemoglobin, Albumin, Lymphocyte, and Platelet score as a non-invasive indicator of Peyronie’s Disease phases." (PMID 40468213, 2025). "The Hemoglobin, Albumin, Lymphocyte, and Platelet score is a cost-effective tool for differentiating Peyronie’s Disease phases, aiding clinical decision-making." (PMID 40468213, 2025).
pituitary tumours (1 paper, 2025). "In patients with pituitary tumours, we also found higher levels of IL-6 and lower levels of albumin." (PMID 41234225, 2025). "The results of the analysis indicated significantly lower levels of DHEA-S (p = 0.007) and albumin (p < 0.001), and higher levels of IL-6 (p < 0.001) in patients with pituitary tumours, relative to the healthy controls." (PMID 41234225, 2025).
plasmacytoma (1 paper, 2018). Plasmacytoma is a localized mass of neoplastic monoclonal plasma cells that represents approximately 5% of all plasma cell neoplasms. "We could not ascribe an etiology for his abdominal pain and diarrhea; it was the presence of a decreased albumin/globulin ratio and a mass confirmed later to be a plasmacytoma that prompted the workup for the final diagnosis." (PMID 29549883, 2018).
Platelet disorders (1 paper, 2024). "Platelet disorders and abnormal levels of ESR, CRP, serum troponin, serum ferritin, D-dimer, and albumin were risk factors for cardiovascular involvement, and consequently, echocardiography is recommended in MIS-C patients with these laboratory indications." (PMID 39570835, 2024).
pneumococcal bacteremia (1 paper, 2018). "In the multivariate analysis, age < 65 years, serum albumin level < 3.0 g/dL, need for intensive respiratory or vasopressor support (IRVS), and C-reactive protein level > 20 mg/dL were identified as independent risk factors for the development of pneumococcal bacteremia." (PMID 29382316, 2018).
pneumococcal pneumonia (1 paper, 2017). A febrile disease caused by STREPTOCOCCUS PNEUMONIAE. "Evaluation of lung tissue injury showed that secondary pneumococcal pneumonia induced a significant cellular damage and alveolar–capillary barrier alterations as demonstrated by the significant higher levels of BAL LDH and albumin when compared to basal levels." (PMID 28848552, 2017).